INS (insulin)
Diseases named in the same sentence as INS in open-access papers (continued):
Sharing a sentence is not in itself a finding about the gene and the disease.
Hyperglycemia (continued). "This was managed with diluted formula feeds (1⁄4 strength) given as hourly bolus feeds, with rapid resolution of hyperglycaemia and no insulin treatment was required." (PMID 26631065, 2015). "We note that hyperglycaemia causes GLUT2 apical insertion to the BBM of proximal tubule cells, and under insulin insensitivity or in lack of insulin, GLUT2 is not internalized, leading to increased reabsorption of glucose." (PMID 25056286, 2014). "Here we report unprecedented high plasma insulin and C-peptide responses (elicited by iv infusion of GLP-1 during hyperglycaemia) in a healthy subject, and propose potential mechanistic differences underlying the differential insulinotropic effects of the two incretins." (PMID 24885055, 2014). "Using hyperglycemic clamps, we observed that EXT carriers were characterized by a reduced first-phase insulin response to hyperglycemia (GSIS) compared to noncarriers matched for age, sex, and BMI." (PMID 25541963, 2014). "Both GSK-3 and Akt in mice brain could be regulated by alterations of blood glucose; streptozotocin-induced hyperglycemia brain increases Akt activity and decreases GSK-3 activity, which could be reversed by lowering blood glucose with insulin administration." (PMID 24983010, 2014). "There is only one prospective study comparing oral antidiabetic drugs to insulin in the treatment of CFRD without fasting hyperglycaemia." (PMID 24620855, 2014). "They need to insulin therapy for their hyperglycemia, but their hyperglycemias were not permanent and after a short period of follow up they were euglycemic and in follow up they had not any typical symptoms for hyperglycemia." (PMID 24734157, 2014). "Rats being fed the same diet period but treated daily with KB-2115 displayed a reduction of hepatic steatosis without evident fasting hyperglycemia, increased glucose production or diminished hepatic insulin sensitivity." (PMID 25538628, 2014). "In the fed state, however, the insulin secretion in response to food intake was not enough to avoid the appearance of hyperglycemia, despite the higher beta-cell mass observed in corticosterone-treated groups." (PMID 24423471, 2014). "We found that insulin treatment markedly improved diaphragm contractility in STZ-treated animals, indicating that in our model, diaphragm weakness is not due to a toxic effect of STZ, but rather, is secondary to the effects of hyperglycemia." (PMID 24886999, 2014). "The HFD+STZ/NA mice did not exhibit a difference in circulating insulin concentration compared to controls, most likely due to pancreatic beta cell damage, as indicated by their relative hyperglycemia compared to controls." (PMID 24824753, 2014). "Based on the decrease in ADP release in parallel with insulin sensitivity, we speculate that decreased ADP induced by BPA may be a critical factor in mediating hyperglycemia." (PMID 24705360, 2014). "Hyperglycemia type does not help in identifying patients who would benefit specially from either NPH insulin or insulin glargine." (PMID 23880900, 2014). "We also found that systemic infusion of APN in the DIO-animal model diminished hyperglycemia (data not shown), which was in agreement with the insulin sensitizing properties of APN." (PMID 24836538, 2014). "The only published prospective study comparing oral antidiabetic drugs to insulin in the treatment of CFRD without fasting hyperglycaemia followed patients for 12 months only." (PMID 24620855, 2014). "As these polyphenolic compounds are abundant in RSL, it is not surprising that RSL administration acutely reduced hyperglycemia and improved insulin sensitivity in DIO mice." (PMID 24637790, 2014). "In the present study, we intended to eliminate chronic hyperglycemia in STZ diabetic rats, with daily injection of NPH insulin, and see if the relief of glucose toxicity acts as a mediator in preserving pancreatic islet beta cells similar to what happens in vanadium treated diabetic rats." (PMID 24842144, 2014).
Hyperglycemia (continued). "In the HFD‐fed mouse model, increases in fasting blood glucose levels and plasma insulin levels have been reported to appear already after 1 week of HFD, resulting in a stable hyperglycemia and a progressively increased hyperinsulinemia over time; Winzell and Ahren 2004)." (PMID 24744873, 2014). "An influence of elevated blood glucose on islet cell proliferation in our studies cannot be ruled out however, given the short period of hyperglycemia experienced even by mice that received an immediate insulin implant immediately following STZ treatment." (PMID 25101835, 2014). "Hyperglycaemia, rather than KATP channel activation, underlies these changes, as they are prevented by insulin therapy and fully reversed by sulphonylureas." (PMID 25145789, 2014). "Males and females also differ in that only in males does rapamycin produce a paradoxical hyperglycemia after insulin injection (data not shown), perhaps reflecting male-specific sensitivity to handling stress or insulin-mediated stress." (PMID 24341993, 2014). "This was also consistent with lack of IRS-1 phosphorylation on Ser-24 in hyperglycemia-induced insulin-resistant adipocytes." (PMID 25330241, 2014). "Next, we confirmed the effects of transplanting 200 islets, which is the optimal number of islets for reversing hyperglycemia, in the absence of insulin treatment." (PMID 24743240, 2014). "Human adipose-derived-MSCs can differentiate into insulin-producing cells which were sensitive to glucose in vitro, and human BM-derived-MSCs can differentiate into β cells, which expressed PDX1 and improved hyperglycemia in diabetic mice." (PMID 25364717, 2014). "Hyperglycemia resulting from DM is a consequence of defects or a lack of insulin secretion and/or action." (PMID 24872834, 2014). "An early study has shown that high doses of salicylates, a kind of Nonsteroidal anti-inflammatory drugs (NSAIDs) reverse hyperglycemia, hyperinsulinemia, and dyslipidemia in obese rodents by sensitizing insulin signaling." (PMID 24404139, 2014). "Several studies have reported a lack of effect of a combination of intravenous glucose and insulin, hypoglycemia, or hyperglycemia on ghrelin secretion." (PMID 24637892, 2014). "In hormone replacement therapy it was estradiol but not estriol is used and as such, as we have described in the manuscript estradiol itself did not have impressive effects in the control of hyperglycemia through hepatic insulin synthesis." (PMID 24711743, 2014). "OIRKO mice also provide a model of osteoblast-specific decreased insulin action, as expected in patients with suboptimally controlled T1D, but without concurrent hyperglycemia." (PMID 24963495, 2014). "The review concluded the evidence does not support the routine use of insulin infusions to prevent hyperglycaemia in VLBW neonates." (PMID 24548745, 2014). "At this time, the plasma insulin concentration in mice inoculated with RRV was similar to that in control mice, although it can be argued that it was inappropriately low relative to the mild hyperglycemia in these mice." (PMID 25181416, 2014). "This would interfere with the ability of insulin to initiate and propagate its normal sequence of actions which may account, at least in part, for STZ-induced hyperglycemia." (PMID 24800231, 2014). "An additional experimental day consisting of a 2 h 15 mM-hyperglycaemic clamp with continuous infusion of saline was designed in order to evaluate the insulin response to hyperglycaemia without incretin hormone infusion." (PMID 24885055, 2014). "This demonstrates that compared to hyperglycemia, insulin action in β-cells is unlikely to play a direct role in inducing ERα mRNA in β-cells." (PMID 24498408, 2014). "The n5 - STZ model shows an unaltered basal hyperglycemia, glucose intolerance, raised glycosylated hemoglobin, a strong reduction of the pancreatic insulin stores, decreased basal insulin levels and lack of plasma insulin response to glucose in-vivo." (PMID 24734054, 2014).
Hyperglycemia (continued). "In combination with inadequate systemic insulin levels and insulin resistance due to the increased secretion of counter-regulatory hormones, the negative manifestations inflicted by hyperglycemia lead to life-threatening conditions in these patients." (PMID 24899891, 2014). "The rats administered nicotinamide (230 mg/kg, ip) 15 min before STZ (65 mg/kg, ip) was found to develop moderate and stable nonfasting hyperglycaemia without any significant change in plasma insulin level." (PMID 25121104, 2014). "However, treatment with common therapies such as insulin or insulinotrophic sulphonylureas (SU), while effective in reducing hyperglycaemia, may impose a greater risk of hypoglycaemia, as neither therapy is self-regulated by ambient blood glucose concentrations." (PMID 22776039, 2013). "In type 1 diabetes, the destruction of insulin-producing beta cells of the pancreas, mainly by autoimmune processes, results in a gross lack of insulin that leads to hyperglycemia." (PMID 23630453, 2013). "With persistent hyperglycemia, increased saturated FFA induce a glucolipotoxic state that is detrimental to beta cells by increasing oxidative stress, subsequently reducing insulin synthesis and secretion thereby compromising both beta cell structure and function." (PMID 23542897, 2013). "We here show that STZ injection in the neonate rat recapitulates hyperglycemia with low, but not null, levels of insulin." (PMID 24278148, 2013). "We found that insulin has no direct cardioprotective effect in the setting of acute hyperglycemia but can recover the ischemic preconditioning effect to limit myocardial infarction." (PMID 24371503, 2013). "Acute hyperglycemia induced by short-term insulin discontinuation surprisingly increases tissue-Doppler-derived indices of left ventricular contractile function in insulin-treated T2D patients with and without heart failure." (PMID 23308171, 2013). "In relation to metabolic and hormonal parameters, although insulin, HOMA index, and leptin were similar between groups, the hypercaloric diet induced hyperglycemia (CD: 90.8 ± 1.4 vs. HD: 97.6 ± 2.4, p = 0.03) and impaired glycemic tolerance (CD: 27198 ± 451 vs. HD: 31867 ± 1463, p = 0.01)." (PMID 23587409, 2013). "In this regard, TNF-α has been hypothesized to exert an inhibitory effect on insulin secretion and insulin-regulated glucose uptake in GDM, thus contributing to the sustained hyperglycemia." (PMID 23691290, 2013). "Dogs with a transplanted (and therefore denervated) pancreas have been reported to have reduced insulin responses or hyperglycaemia after oral, but not i.v., glucose, suggesting impaired incretin action." (PMID 23704713, 2013). "The main finding of this study is that xylazine administration produced an acute hyperglycemia without significant changes in blood insulin, glucagon, and GLP-1 in both insulin-dependent diabetic and normoglycemic monkeys." (PMID 24138083, 2013). "Hyperglycemia and lipid peroxidation were produced as a result of absence of insulin and high level of ROS, respectively." (PMID 24364912, 2013). "According to Funke and Melzig, this disorder is characterized by chronic hyperglycemia with disturbances of metabolism resulting from lack of insulin secretion and insufficient cellular production of insulin." (PMID 23737820, 2013). "The survival rate at 65 weeks was 92% in males and 97% in females, showing that the rats survive hyperglycemia without insulin treatment." (PMID 23691526, 2013). "In the event that the patient develops hyperglycemia (10.5 mmol/L blood glucose), 75% of centers would not start an insulin perfusion, 17% would start insulin without any protocol, and 8% would start insulin following a written protocol." (PMID 23497713, 2013). "This therefore implicates the 5-fold increase in insulin in the SF dams and/or transient hyperglycaemia in the non-fasted insulin resistant state as potential modulators of hypothalamic function in this model." (PMID 23423541, 2013).
Hyperglycemia (continued). "Here we have used genetically modified mice with a defect in cholesterol synthesis to determine the consequences of decreased brain cholesterol, in the absence of the hyperglycemia and impaired insulin signaling found in diabetic mice." (PMID 23585733, 2013). "Taken together, these results suggest that treatment with a short course of anti-CD20 alone, 6 weeks of oral insulin alone, or the combination, fails to reverse hyperglycemia in new-onset diabetic NOD mice." (PMID 23405091, 2013). "The acute correction of hyperglycaemia and improvement of glucose tolerance observed 1 day after transplantation and following E2 treatment occur without an increase in graft insulin secretion." (PMID 23132340, 2013). "Collectively, the results suggested that short-term supplementation of genistein possesses the capacity to reduce hyperglycemia in the DMMH group without insulin treatment but not in DMH group." (PMID 23737649, 2013). "Since we intended to investigate hyperglycemia as a result of insulin discontinuation as opposed to normoglycemia, we chose not to use FGD-PET in the present studies." (PMID 23308171, 2013). "Since the brain is mainly a glucose-dependent organ, a severe hyperglycemia in T1DM, mild hyperglycemia typical of T2DM, and recurrent hypoglycemia induced by inappropriate insulin therapy are the major factors responsible for the development of DM-induced cerebral disorders." (PMID 24191197, 2013). "Patients with the same insulin sensitivity show either normal or impaired glucose tolerance with or without hyperglycemia." (PMID 23516528, 2013). "Elevated flux has been identified to be associated with increased REE, insulin resistance or lack of insulin secretion; these alterations were worsened with the magnitude of hyperglycemia." (PMID 23251271, 2013). "The growth curves and blood glucose levels in the animals in this study were similar to those reported by others using streptozotocin diabetic rats receiving insulin without or with coadministration of an agent that does not affect hyperglycemia." (PMID 24303153, 2013). "Yet insulin is not recommended as the initial treatment, unless hyperglycemia is severe, by implication because of the side-effects, management resources and patient preference." (PMID 23841986, 2013). "Therefore, impairment in insulin expression at the mRNA and protein levels occurs early in TAM-treated Glis3fl/fl/Pdx1CreERT+ mice, an effect that precedes the onset of hyperglycaemia and the apoptosis that the latter induced." (PMID 23197416, 2013). "Hyperglycemia does not develop because the reduced effect of insulin at target tissues is offset by an increase in insulin secretion." (PMID 24348462, 2013). "Eight weeks after treatment they displayed significantly lower body weight and severe hyperglycaemia (>600 mg/dl), whilst their plasma insulin was almost completely absent." (PMID 23197416, 2013). "In the insulin-resistant state, when insulin no longer regulates carbohydrate and lipid metabolism, hyperglycemia, hepatic steatosis and dyslipidemia ensue." (PMID 24284392, 2013). "Preconditioning with diaxoxide enhanced insulin contents in transplants of rat islets to non-diabetic rats and lowered hyperglycemia vs. non-preconditioned islets in streptozotocin-diabetic rats." (PMID 23935835, 2013). "Glucose feeding produced transient hyperglycemia and insulin levels of 2.2–2.3 ng/mL (not significantly different from the fed state)." (PMID 23861810, 2013). "Despite profound hyperglycemia, plasma insulin in the CLP glucose-infused mice (3.7 ± 1.2 ng/ml) was not higher than sham glucose infused mice (2.1 ± 0.3 ng/ml)." (PMID 23826335, 2013). "Animal studies have reported that the detrimental effects of acute hyperglycemia on the exacerbation of myocardial infarction or the blockade of ischemic preconditioning are independent of insulin." (PMID 24371503, 2013).
Hyperglycemia (continued). "Acute correction of hyperglycemia with insulin does not substantially improve 18F-FDG PET image quality because of different dynamics of normalization of plasma versus intracellular glucose concentrations." (PMID 23762852, 2013). "In the fourth case, graft removal did not lead to hyperglycemia, a recovery of pancreatic insulin production that is known to occur in a proportion of rats exposed to STZ." (PMID 23991016, 2013). "Recent guidelines and treatment algorithms emphasize the need for early addition of insulin therapy in people who do not meet target goals, in order to reduce the time people are exposed to hyperglycemia." (PMID 24223860, 2013). "Initially, E2-treated graft beta cells are non-functional and show no insulin-secretory response to the glucose challenge, probably as a result of hyperglycaemia-induced glucose desensitisation and/or lack of islet vascularisation." (PMID 23132340, 2013). "However, insulin was almost undetectable in the blood of STZ rats, which is in line with the severe hyperglycemia found in these animals." (PMID 23620811, 2013). "The authors reported that neither insulin treatment (despite normalization of hyperglycemia) nor antioxidant therapy (vitamin C) was able to sufficiently ameliorate oxidative stress or normalize endothelial dysfunction." (PMID 22489136, 2012). "Asians, especially from northeast Asia, have a low insulin secretory capacity and develop diabetes with little or no hyperglycemia prior to the failure of glycemic control." (PMID 22550941, 2012). "When plant treatment is introduced and the dosage titrated up, evidence of reduced hyperglycemia or a reduction of insulin dosage without deterioration of glycemic control can be used as indices of efficacy." (PMID 22899950, 2012). "Furthermore, after ten days of constant maternal hyperglycemia, fetal GSIS and arginine-stimulated insulin secretion (ASIS) were decreased compared to normal fetuses." (PMID 23133755, 2012). "It has been demonstrated that the use of insulin to lower glucose concentrations decreased negative outcomes in patients with hyperglycemia and myocardial infarction (see Section 3); however, a mechanism by which hyperglycemia may be a causal factor in poor outcomes in AMI remains a topic of debate." (PMID 22830071, 2012). "Our finding that insulin and GLP-1 mediated glucose uptake is impaired by hyperglycemia may indeed be confounded by the trend towards increased basal glucose uptake under hyperglycemic conditions." (PMID 22937169, 2012). "Hyperglycemia spontaneously develops in SDT rats, predominantly due to an insulin secretary defect." (PMID 23056035, 2012). "In these “non responders” subjects, the application of SNP neither controlled hyperglycemia nor resulted in the increase of plasma insulin level." (PMID 23675270, 2012). "Fetal hyperglycemia can stimulate insulin secretion by the fetal pancreas, subsequently leading to normalization of fetal glycemia." (PMID 22970290, 2012). "In addition, chronic hyperglycemia induced ER- stress in cultured INS-1 cells and ER stress-induced activation of ATF6 impaired insulin gene expression via upregulation of the orphan nuclear receptor small heterodimer partner (SHP)." (PMID 22474424, 2012). "We have previously demonstrated that osmotic insulin pump therapy while correcting hyperglycemia does not restore normal insulin-triggered tyrosyl phosphorylation patterns." (PMID 22606220, 2012). "Once β-cell mass decreases below a critical level and insulin production no longer meets metabolic demands, hyperglycemia was occurred in patients." (PMID 22922276, 2012). "The use of the single high-dose STZ injection model was chosen here primarily to address the consequences of hyperglycemia and lack of insulin on cardiac remodeling." (PMID 22347376, 2012). "The patients with hyperglycemia seemed to be more insulin resistant compared with those without hyperglycemia." (PMID 21960993, 2012).